SNORD88B (small nucleolar RNA, C/D box 88B)
Synonyms: HBII-180B
Gene: Small nucleolar RNA gene on chromosome 19 (50,799,032 to 50,799,122, reverse strand). Ensembl gene ENSG00000221381.
Gene Ontology:
Biological process: RNA processing
Cellular component: nucleolus
Homologues: Orthologues: chimpanzee SNORD88B (99% identical), macaque SNORD88B (95% identical), dog SNORD88B (88% identical), pig SNORD88B (86% identical), guinea pig SNORD88B (85% identical), mouse Snord88a (84% identical), mouse Snord88c (84% identical), mouse Gm23991 (74% identical), rat LOC120100474 (60% identical), mouse Gm54694 (44% identical). Paralogues in human: SNORD88A (91% identical), SNORD88C (88% identical).
Diseases named in the same sentence as SNORD88B in open-access papers:
SNORD88B is named in the same sentence as 3 diseases in open-access papers, as found by Europe PMC text mining. Sharing a sentence is not in itself a finding about the gene and the disease. The quoted sentences say what the papers report.
liver cancer (2 papers, 2025). An epithelial or non-epithelial malignant neoplasm that arises from the liver. "Recent studies have shown that SNORD88B is highly expressed in liver cancer stem cells (CSCs) and liver cancer samples, where it promotes the binding of XRCC5 to the STK4 promoter, thereby inhibiting STK4 transcription." (PMID 40584410, 2025).
hepatocellular carcinoma (1 paper, 2025). A malignant tumor that arises from hepatocytes. "SNORD88B drives self‐renewal of liver CSCs and accelerates hepatocellular carcinoma (HCC) progression through a nonclassical mechanism." (PMID 40584410, 2025).
SNORD88B also shares sentences with these, for which no sentence is quoted: leukemia (1 paper).